IL3RA (interleukin 3 receptor subunit alpha)
Diseases named in the same sentence as IL3RA in open-access papers (continued):
Sharing a sentence is not in itself a finding about the gene and the disease.
tumor (17 papers, 2018 to 2025). "Another important group of immune-associated genes regulated by anisomycin included KITLG, IL-6, IL-32, and IL-3RA, which encode cytokines and cytokine receptors to mediate potential survival signals or growth signals in tumour cells." (PMID 30006566, 2018). "However, CAR-NK-92 cells engineered to target CD123 (IL3RA) may pose a risk of off-tumor toxicity as up to 9% of healthy hematopoietic progenitor cells also express CD123." (PMID 34372571, 2021). "According to the data on THPA, most of these genes (VWF, GNG11, FGF7, and IL3RA) were also higher in PAAD tissues at the protein level (compared to non-tumor tissues)." (PMID 37070074, 2023). "On the contrary, in the low-risk group, the expressions of IL3RA, CX3CR1, ARRB1, LIFR, and VIPR1 were higher than those in the high-risk group, which signified that they have a tumor suppressor effect." (PMID 35833114, 2022). "ADRB2, ANGPTL4, BDNF, CBLC, CX3CR1, and IL3RA were found markedly different expression between the tumor and normal group." (PMID 35833114, 2022). "The in vitro cytotoxicity of the IL3RA-ADC BAY-943 was assessed in a panel of human tumor cell lines with different IL3RA expression levels." (PMID 33233768, 2020). "In vivo, IL3RA-ADC improved survival and reduced tumor burden in IL3RA-positive human AML cell line-derived (MOLM-13 and MV-4-11) as well as in patient-derived xenograft (PDX) models (AM7577 and AML11655) in mice." (PMID 33233768, 2020). "Impressively, treatment with BAY-943 induced complete tumor remission in 12 out of 13 mice in an IL3RA-positive HL model." (PMID 33233768, 2020). "Moreover, we ascertained that the different expression of ADRB2, ANGPTL4, BDNF, CBLC, CX3CR1, and IL3RA in tumor and normal group was consistent both in PCR and UALCAN." (PMID 35833114, 2022). "In the AM7577 PDX model, IL3RA-ADC administered at 10 mg/kg intraperitoneally (i.p.)reduced tumor burden compared to the vehicle or isotype control ADC, as indicated by a decreased number of human CD45 (hCD45)/human IL3RA (hIL3RA)-positive cells in blood on day 56 (both p < 0.001)." (PMID 33233768, 2020). "Furthermore, IL3RA-ADC induced complete tumor remission in 12 out of 13 mice in an IL3RA-positive HL cell line-derived xenograft model (HDLM-2)." (PMID 33233768, 2020). "Phosphosites from immune system-associated proteins (e.g., IL3RA, PECAM1, PTPN1, SIGLEC7, and JUP) showed an overall higher phosphorylation in tumor tissues than in normal adjacent tissues, suggesting enhanced immune signaling is likely to occur during tumor development." (PMID 33953186, 2021). "Moreover, the expression levels of IL3RA in different subsets, such as liver sinusoidal EC and macrovascular EC, are different, which remind us that there exist many uncertainties of “on-target, off-tumor toxicity” because of the cell heterogeneity and thus need to further identification." (PMID 34975912, 2021). "Generally, the immune cells were more enriched in the tumor stroma compared to the tumor epithelial nests, in particular for the CD20+ B cells, CD57+ NK cells and IL3RA+ plasmacytoid dendritic cells (pDCs)." (PMID 32686767, 2020). "In the two IL3RA-ADC treatment groups, total tumor eradication was observed in twelve mice out of thirteen (92%) at the end of the study." (PMID 33233768, 2020). "The increased survival was accompanied by a reduction in the growth of IL3RA-positive AML cells and tumor size in the systemic and subcutaneous models, respectively." (PMID 33233768, 2020). "DCs were further subdivided into cDC1 (cross-presenting dendritic cells; cluster 5 in Paratumor and cluster 11 in Tumor; CLEC9A+ and XCR1+), cDC2 (cluster 1 in Paratumor and cluster 1 in Tumor; CD1C+) and plasmacytoid DC (pDC; cluster 4 in Paratumor and cluster 13 in Tumor; LILRA4+ and IL3RA+)." (PMID 33429363, 2021). "In IL3RA-positive AML mouse models, BAY-943 improved survival and reduced tumor burden." (PMID 33233768, 2020).
tumor (continued). "Furthermore, in the MV-4-11 model, treatment with the unconjugated IL3RA-Ab TPP-9476 at 5 mg/kg, Q7D×2 showed no tumor growth inhibition, indicating that the antitumor activity of IL3RA-ADC is conveyed by the targeted delivery of the KSPi payload and not the IL3RA-Ab." (PMID 33233768, 2020).
cancer (8 papers, 2011 to 2025). A tumor composed of atypical neoplastic, often pleomorphic cells that invade other tissues. "Here, we exploited a novel pyrrole subclass payload that potently inhibits the kinesin spindle protein (KSP/KIF11/Eg5) in biochemical and cellular assays to develop an ADC to target IL3RA on cancer cells." (PMID 33233768, 2020). "Further studies in larger series of patients are warranted to elucidate this question and determine the specific role of those cancer associated genes (INPP5A, CDX1, MB, CAMK2A, APOL6 vs. VPS53, FAM57A, GEMIN4, SFRS13, ELP2P, GLOD4, CSF2RA and IL3RA), differentially altered in both groups of tumors." (PMID 21811587, 2011).
infection (4 papers, 2011 to 2022). The state of being infected such as from the introduction of a foreign agent such as serum, vaccine, antigenic substance or organism. "Our study is the first to report on difference in TLR5, CXCL17, CCL26, IL1RL2, or IL3RA levels in sexes during infection." (PMID 36171541, 2022). "The number of regulated genes declined at 48 h post infection to 5.4% and increased again in the chronically infected cells to constitute 10.1% of the genes in this category, with a modified spectrum of highly induced genes, namely IL3RA, IL6, IL24 and SPRY4." (PMID 23326599, 2013). "However, IL13RA, IL3RA, IL4, STAT1, STAT4 were down-regulated at this time point of infection." (PMID 21439068, 2011).
hematological malignancies (3 papers, 2020 to 2023). "Another reliable therapeutic target in the treatment of hematological malignancies is the interleukin 3 (IL-3) receptor α-chain (IL3RA) or CD123." (PMID 34944865, 2021). "Overall, the preclinical results support the further development of BAY-943 as an innovative approach for the treatment of IL3RA-positive hematologic malignancies." (PMID 33233768, 2020). "Overall, these preclinical results support the further development of BAY-943 for the treatment of IL3RA-positive hematologic malignancies." (PMID 33233768, 2020). "CD123/IL3RA: The IL3 receptor alpha chain is a transmembrane protein that is aberrantly over-expressed in AML and a few other hematological malignancies but has limited expression in cells of normal hematopoiesis." (PMID 37987319, 2023). "Taken together, these results suggest that IL3RA is a very attractive target for an antibody–drug conjugate (ADC) approach for the treatment of AML and other IL3RA-positive hematologic malignancies." (PMID 33233768, 2020).
hematologic cancer (2 papers, 2020 to 2026). "Blastic plasmacytoid dendritic cell neoplasm (BPDCN) is an aggressive orphan hematologic cancer with a poor prognosis, and is derived from plasmacytoid dendritic cells that overexpress interleukin-3 receptor subunit alpha (IL3RA or CD123)." (PMID 41493719, 2026). "Furthermore, IL3RA-Ab bound specifically to the IL3RA-expressing human hematologic cancer cell lines MOLM-13, MV-4-11, and KG-1 as determined by flow cytometry." (PMID 33233768, 2020).
cardiovascular disorder (1 paper, 2024). A disease involving the cardiovascular system. "Among these, CPA3, CAMP, and IL3RA have been found to exhibit strong connections with cardiovascular disorders." (PMID 38753730, 2024).
genetic disorder (1 paper, 2017). "In this Taiwanese family, three genes (CSF2RA, CRLF2, and IL3RA) are homozygously deleted in the pseudoautosomal region of the human X chromosome, concordant with that PAP is a rare genetic disorder inherited at a recessive pattern." (PMID 28233860, 2017).
neurological diseases (1 paper, 2024). "There is currently limited research on the relationship between E‐selectin and IL‐3Ra, as well as IL‐3Ra and IL‐5Ra in neurological diseases." (PMID 38340139, 2024).
IL3RA also shares sentences with these, for which no sentence is quoted: cervical cancer (2 papers); prostate carcinoma (2); viral infection (2); B-cell acute lymphoblastic leukemia (1); chronic myeloid leukemia (1); chronic myelomonocytic leukemia (1); degenerative disease of (1); endometrial cancer (1); hereditary pulmonary alveolar proteinosis (1); Infertility (1); lumbar spinal stenosis (1); myelodysplastic syndrome (1); myeloproliferative neoplasm (1); squamous cell carcinoma (1); Thrombocytopenia (1); thyroiditis (1); Turner syndrome (1).